RHO (rhodopsin)
Diseases named in the same sentence as RHO in open-access papers (continued):
Sharing a sentence is not in itself a finding about the gene and the disease.
infection (11 papers, 2019 to 2026). The state of being infected such as from the introduction of a foreign agent such as serum, vaccine, antigenic substance or organism. "Briefly, cells were transduced with a lentiviral library containing all single-residue missense, nonsense, and synonymous RHO variants (constitutively expressed), using a low multiplicity of infection to ensure integration of only one variant per cell." (PMID 40093169, 2025). "Infection of rice plants with the rhodopsin-deficient mutant homolog (CarO) of Fusarium fujikuroi (ambiguously referred to as H or N) showed more severe symptoms than the control strain, indicating a potential role of rhodopsin in the regulation of plant infection." (PMID 31878885, 2019). "A top performing variant identified using this pipeline, K912, was used to deliver SaCas9 and edit the rhodopsin gene in macaque retina, resulting in editing efficiency similar to infection rates detected by the scAAVengr workflow." (PMID 34664552, 2021). "Although these protein analyses and our studies were performed at different infection times, GTPases family members such as CDC42, RAC1 and RHO were found dysregulated suggesting them as essential players in the infection." (PMID 40396886, 2025). "In P24 control-injected rd10/rd10 retina, Rhodopsin was abnormally translocated from the OS to the ONL, a phenomenon that was partially rescued by infection with the AAV8-KITL virus." (PMID 32242818, 2020). "Although we have no direct prove that UmRh1 is part of the infection process since we have studied only the isolated rhodopsin, we can speculate on its potential role in the mechanism of pathogenesis." (PMID 35281268, 2022).
neurodegenerative disease (6 papers, 2011 to 2025). A disorder of the central nervous system characterized by gradual and progressive loss of neural tissue and neurologic function. "Protein aggregation is a hallmark of many neurodegenerative diseases and rhodopsin aggregation appears to also belong in this category." (PMID 38365903, 2024). "Rhodopsin, a G-protein coupled receptor in the rod cells of the retina is a biomarker associated with retinal thinning and degeneration, suggesting its potential in the early detection and progression monitoring of neurodegenerative diseases." (PMID 32351353, 2020). "With the development of novel techniques, such as cSLO, which allows the quantification of rhodopsin, efforts should be made to determine whether rhodopsin might have an increased sensitivity for the diagnosis and monitoring of neurodegenerative diseases." (PMID 32351353, 2020). "Future studies should investigate and determine whether the rates of rhodopsin degeneration differ among neurodegenerative diseases." (PMID 32351353, 2020). "Therefore, rhodopsin has emerged as a biomarker, which may serve as the link between retinal thinning and neuronal pathology seen in neurodegenerative diseases." (PMID 32351353, 2020).
autosomal dominant disease (2 papers, 2014 to 2021). Autosomal dominant form of disease. "For truncations in CRX and RHO, loss-of-function mutations are responsible for autosomal recessive diseases while dominant-negative mutations lead to autosomal dominant diseases." (PMID 33681214, 2021).
cardiac disease (2 papers, 2020 to 2025). "RHO/ROCK specific inhibitors show promise in the prevention of heart disease." (PMID 32013934, 2020).
genetic disease (2 papers, 2016 to 2024). "Through our analysis of CFH, rhodopsin, and RPE65, we were able both to draw conclusions relating to critical residues in protein structures and to predict misfolding-causing mutations in genetic disease." (PMID 27905547, 2016).
infectious disease (2 papers, 2023 to 2024). A disorder directly resulting from the presence and activity of a microbial, viral, or parasitic agent in humans.
diseases of immune system (1 paper, 2024). "The GSEA analysis revealed a predominant concentration of the TFRC gene expression phenotype in the ferroptosis, diseases of immune system, jak stat signaling pathway, ECM affiliated, RHO GTPases activate NADPH oxidases, JNK pathway, and condensation of chromosomes." (PMID 39131609, 2024).
inflammation (1 paper, 2022). Aberrant reaction of the microcirculation characterized by movement of fluid and leukocytes from the blood into extravascular tissues. "Notably we found TOPORS and UBR1 dysregulated in the USH1B organoids (GO:0010498); mutation of the former is a cause of autosomal dominant RP, and the latter promotes rhodopsin protein degradation in the OS via the UPS during retinal inflammation." (PMID 36240775, 2022).
RHO also shares sentences with these, for which no sentence is quoted: autosomal recessive retinitis pigmentosa (3 papers); cardiovascular disease (3); retinitis pigmentosa 1 (3); colon carcinoma (2); familial hypercholesterolemia (2); Huntington disease (2); hyperopia (2); Macular dystrophy (2); retinoschisis (2); Stargardt disease (2); Usher syndrome type 2 (2); vitamin A deficiency (2); age (1); amyotrophic lateral sclerosis (1); anaplastic large cell lymphoma (1); Anaplastic Thyroid Cancer (1); asthma (1); atherosclerosis (1); atrophic macular degeneration (1); autism (1); autoimmune hyperthyroidism (1); autosomal recessive disease (1); bladder cancer (1); cervical cancer (1); choroideremia (1); cone dystrophy (1); COVID-19 (1); cutaneous squamous cell carcinoma (1); cyst (1); cystoid macular edema (1).
A further 51 diseases each share a sentence with RHO in 1 paper.